EGFR (epidermal growth factor receptor)
Diseases named in the same sentence as EGFR in open-access papers (continued):
Sharing a sentence is not in itself a finding about the gene and the disease.
Obesity (56 papers, 2009 to 2025). Accumulation of substantial excess body fat. "It has been suggested that VSMC-EGFR contributes to obesity- and T2DM-associated vascular alterations, and that hyperglycemia is correlated with an enhanced vascular EGFR activity." (PMID 41429904, 2025). "As described in the introduction, in vivo studies provided substantial evidence for a role of vascular EGFR in T2DM/obesity-associated functional and structural vascular remodeling." (PMID 41429904, 2025). "Comparative analysis of primary murine vascular cells sheds light on the roles of epidermal growth factor receptor, sex and the synergism of stressors for obesity-associated transcriptomic and phenotypic vascular alterations." (PMID 41429904, 2025). "The epidermal growth factor receptor (EGFR) tyrosine kinase inhibitor decreased obesity in a murine model of leptin receptor-deficient T2DM." (PMID 36747287, 2023). "The in vivo experiments demonstrate that hyperlipidemia causes EGFR activation and EGFR inhibition attenuates obesity-induced renal injury." (PMID 27014908, 2016). "Thus, these pathological relevant and T2DM/obesity-associated processes were predicted to result from the synergistic, EGFR-dependent action of metabolic and humoral stressors." (PMID 41429904, 2025). "In the non-obesity group, multivariate analysis demonstrated that anlotinib therapy (p = 0.002), PS score of 0 (p = 0.005), EGFR mutation (p = 0.022), number of metastases ≤3 (p < 0.001), and less lines of previous chemotherapy (p = 0.013) were independent predictors of improved OS." (PMID 35431919, 2022). "In adipose tissue, AREG expression is markedly upregulated during HFD-induced obesity in wild type mice but is profoundly downregulated in iRhom2-deficient mice, suggesting a possibly leading role of EGFR-dependent cellular processes over TNF in the modulation of metabolic pathways during obesity." (PMID 33330676, 2020). "Accordingly, EGFR replacement treatment improved the regenerative response of the fatty liver in an obesity mouse model after 70 and 80% hepatectomy." (PMID 39843785, 2025). "EGFR signaling has been linked to hepatic stellate cell activation during MASH and adipose tissue activation during obesity." (PMID 39952408, 2025). "Obesity leads to vascular dysfunction mediated partially by the vascular smooth muscle cell (VSMC) EGF-receptor (EGFR)." (PMID 41429904, 2025). "As alluded to above, EGFR signaling is also required for beta cell expansion, as mice expressing a dominant negative form of EGFR fail to acquire compensatory beta cell expansion during pregnancy and obesity." (PMID 37233668, 2023). "In the first-line setting, EGFR TKIs yielded better survival outcomes in overweight patients in two different trials; in the second-line, obesity negatively influenced outcomes." (PMID 37444532, 2023). "In genetic mouse models we described the role of vascular smooth muscle (VSMC) EGFR for proper physiological function and structure as well as for pathophysiological alterations by obesity or angiotensin II." (PMID 33790318, 2021). "Meanwhile, the role of EGFR signaling in obesity and obesity-induced metabolic syndrome is currently unclear." (PMID 33330676, 2020). "We investigated the role of VSM-EGFR during obesity-induced renovascular dysfunction, as well as EGFR–hyperglycaemia crosstalk." (PMID 32548701, 2020). "Our work shows that the persistent signaling by mutated EGFR in TKI‐resistant tumor cells relies on EGFR palmitoylation and can be targeted by Orlistat, an FDA‐approved anti‐obesity drug." (PMID 29449326, 2018). "Our work demonstrate that the persistent signaling by mutated EGFR in TKI‐resistant tumor cells relies on palmitoylation of EGFR and can be targeted by Orlistat, an FDA‐approved anti‐obesity drug." (PMID 29449326, 2018). "This study demonstrates that EGFR is deeply involved in the pathogenesis of obesity-related renal injury and provides strong evidence for targeting the EGFR pathway for the treatment of this disease." (PMID 27014908, 2016).
Obesity (continued). "This study was performed to demonstrate if EGFR plays a role in the pathogenesis of hyperlipidemia/obesity-related cardiac injuries." (PMID 27087279, 2016). "In conclusion, the results from this experiment help to elucidate the mechanisms behind TLR4/c-Src/EGFR signaling in the pathogenesis of obesity-related renal injury." (PMID 27014908, 2016). "This study aims to demonstrate the potential role and mechanism of EGFR in the pathogenesis of obesity-related kidney injury." (PMID 27014908, 2016). "Our results contribute to understand the detrimental role and mechanism of EGFR activation in obesity-related cardiac disorders." (PMID 27087279, 2016). "The connection between EGFR activity and obesity is further reinforced by the observation that obesity is strongly associated with an increased mortality rate in cancer patients." (PMID 22754566, 2012). "Our present results, which concur with pharmacological findings, support the hypothesis that VSMC-EGFR is involved in VSMC responses to T2DM/obesity-associated stressors, because the effects were much stronger in WT VSMC compared to EGFR-KO VSMC." (PMID 41429904, 2025). "Notably, obesity-specific macrophages regulated hormone-mediated responses in adipocytes through targeted EGFR signaling." (PMID 41459526, 2025). "The highest-ranked target was EGFR, which appeared in 36 forms at an intersection of 115 PG-active saponins and possible anti-obesity targets, which may be a core anti-obesity target." (PMID 38674532, 2024). "The most involved anti-obesity proteins include EGFR, STAT3, JUN, GSK3B, PPARG, and HSP90AA1." (PMID 38674532, 2024). "Current research reveals that it is closely related to muscle development, obesity, metabolic syndrome, and also serves as a prognostic biomarker in clear cell renal cell carcinoma, but its function in EGFR‐TKIs resistance is unknown." (PMID 39036343, 2024). "Active ingredients in WP, such as oxidized glutathione, may improve symptoms of HFD-induced obesity by acting on targets such as EGFR, NOS3, MMP2, PLG, PTGS2, and AR." (PMID 38162665, 2023). "In a study aiming to determine if EGFR mediates the pathogenesis of hyperlipidemia/obesity-related cardiac diseases, EGFR inhibition significantly ameliorated myocardial fibrosis, apoptosis, and inflammation in two rat models of obesity." (PMID 34408653, 2021). "As the importance of endothelial (EC) EGFR in vivo is unknown, we analyzed the impact of EC-EGFR knockout in a conditional mouse model on vascular and renal function under control condition as well as in obesity and in comparison to VSMC-KO." (PMID 33790318, 2021). "If the production of these ligands is upregulated in obesity, there are significant implications for EGFR-mediated cell proliferation, invasion, and metastasis of epithelial malignancies via downstream activation of the ERK, PI3 kinase/AKT, and JAK/STAT pathways." (PMID 27525640, 2017). "Our data suggest that EGFR may be a therapeutic target for obesity-related cardiovascular diseases, and that the novel EGFR inhibitor 542 shows promises to the treatment on obesity-induced cardiac complications." (PMID 27087279, 2016). "The effect of EGFR activation is the activation of the NF-κB pathway and the upregulation of key genes involved in the inflammatory response and oxidative stress, contributing to the pathogenesis of obesity-related renal injury." (PMID 27014908, 2016). "We foundthat EGFR inhibition diminished renal injury by reductionof inflammation, oxidative stress, apoptosis and fibrosis both in vivo and in vitro and that our results provided further support tounderstand the detrimental role and mechanism of EGFR activation in obesity-related kidney diseases." (PMID 27014908, 2016). "AG1478 and 542 also attenuated cardiac dysfunction in HFD-fed ApoE−/− mice, suggesting that EGFR antagonism may be a therapeutic strategy for obesity-induced heart injury." (PMID 27087279, 2016).
Obesity (continued). "Moreover, obesity can regulate the mutation of oncogenes, such as Kirsten rat sarcoma virus (KRAS), epidermal growth factor receptor (EGFR), SET domain-containing 2 protein (SETD2), and BRCA1-associated protein 1 (BAP1), which also increases the risk of cancer development." (PMID 40863244, 2025). "We investigate the impact of obesity-associated metabolic and humoral stress on primary murine VSMC with conditional EGFR knockout (KO) and wildtype (WT) VSMC, focusing on early-phase impact to test the hypothesis of an EGFR-dependent stressor synergism." (PMID 41429904, 2025). "A recent study also suggests that dysregulation of vascular, as opposed to endothelial, EGFR might be the dominant factor in the development of vascular pathologies associated with obesity an important risk factor for developing T2DM." (PMID 34408653, 2021). "Increased plasma HB-EGF has been associated with obesity and coronary artery disease; however, no studies have addressed whether modulation of EGFR signaling impacts atherogenesis." (PMID 34312731, 2021). "However, it is still unknown whether EGFR inhibition is able to alleviate the development of obesity-related disorders, such as hyperlipidemia-induced kidney diseases." (PMID 27014908, 2016). "Our data suggest that EGFR may be a therapeutic target for obesity-related cardiovascular diseases." (PMID 27087279, 2016). "However, it is unclear if EGFR is involved in obesity-related kidney injury." (PMID 27014908, 2016). "While the EGFR in VSMCs promoted blood pressure increase in a model of chronic RAAS activation, it seems to be slightly protective in obesity, as the blood pressure increase is more pronounced if the EGFR is lacking in VSMCs of mice on a high-fat diet." (PMID 37626737, 2023). "Therefore, in addition to providing direct evidence for a role in diet-induced obesity, our findings suggest that treatments that inhibit EGFR activity may not only directly inhibit tumor growth but could have an additional effect to improve metabolic homeostasis." (PMID 35948530, 2022). "Through a network pharmacology analysis, the anti-obesity effect of hispidulin was predicted to act on estrogen, prolactin, Rap1, and PI3K-Akt signaling pathways by targeting AKT1, SRC, EGFR, and GSK3B." (PMID 34944408, 2021). "According to the PPI network analysis of hispidulin anti-obesity targets, SRC (proto-oncogene tyrosine-protein kinase Src), EGFR (epidermal growth factor receptor), and AKT1 (AKT serine/threonine kinase 1) were the top three genes based on the degree." (PMID 34944408, 2021). "AKT1, SRC, EGFR, and GSK3B were identified as key anti-obesity target genes of hispidulin, and estrogen, prolactin, Rap1, and PI3K-Akt signaling pathways were predicted to be involved in the anti-obesity effects of hispidulin." (PMID 34944408, 2021). "Overall, PRK-CA, EGFR, CDC42, and VEGF-A were found to be upregulated in this study and imply a role of focal adhesion in NAFLD development and obesity." (PMID 31771247, 2019). "However, it is unknown if EGFR play a role in the pathogenesis of obesity-related cardiac injury." (PMID 27087279, 2016). "The in vivo studies using both wild type (WT) and apolipoprotein E (ApoE) knockout mice fed with high fat diet (HFD) showed the beneficial effects of small-molecule EGFR inhibitors, AG1478 and 542, against obesity-induced myocardial injury." (PMID 27087279, 2016). "This study has confirmed the detrimental effect of EGFR activation in the pathogenesis of obesity-induced cardiac inflammatory injuries in experimental mice, and has demonstrated the TLR4/c-Src-mediated mechanisms for PA-induced EGFR activation." (PMID 27087279, 2016). "At the cellular level transcriptional actions of EGFR were potentiated by glucose and pathway analysis identified the serum response factor (SRF) as an activated vascular transcription regulator during T2DM/obesity." (PMID 41429904, 2025).
Obesity (continued). "The integration of metabolomics and network pharmacology has identified six hub targets, namely AKT1, EGFR, ESR1, STAT3, IGF1, and MAPK1, that may be critical for the effects of EGCG on obesity-related precocious puberty." (PMID 40807299, 2025). "In summary, EGCG may serve a role in preventing obesity-related precocious puberty through targets such as AKT1, EGFR, ESR1, STAT3, IGF1, and MAPK1 that acted on multiple signaling pathways, including the estrogen, PI3K-Akt, MAPK, and Jak-STAT pathways." (PMID 37334310, 2023). "According to the results of integrated metabolomics and network pharmacology, 6 hub targets, including AKT1, EGFR, ESR1, STAT3, IGF1, and MAPK1, may play significant roles in the effects of EGCG on obesity-related precocious puberty." (PMID 37334310, 2023). "The integrated metabolomics and network pharmacology indicated that AKT1, EGFR, ESR1, STAT3, IGF1, and MAPK1 may be key targets for EGCG in preventing obesity-related precocious puberty." (PMID 37334310, 2023). "EGCG may contribute to preventing obesity-related precocious puberty through targets such as AKT1, EGFR, ESR1, STAT3, IGF1, and MAPK1 and multiple signaling pathways, including the estrogen, PI3K-Akt, MAPK, and Jak-STAT pathways." (PMID 37334310, 2023). "The relevance of vascular smooth muscle cells (VSMC)-EGFR for basal vascular function, for angiotensin II (AII)- or obesity-induced structural and functional vascular remodeling, as well as for complete renal end organ damage succeeding vascular remodeling, was shown." (PMID 33790318, 2021). "In summary, this study has confirmed the detrimental effect of EGFR activation in the pathogenesis of obesity-induced cardiac inflammatory injuries in experimental mice, and has demonstrated the TLR4/c-Src-mediated mechanisms for PA-induced EGFR signaling pathway activation in H9c2 cells." (PMID 27087279, 2016). "The mammalian EGFR and components of the mammalian EGF signaling pathway are known to enhance glucose absorption in the gut, induce obesity in ovariectomized and aged female mice, are decreased in adipose tissues of calorie restricted mice, and are associated with hyperglycemia in humans." (PMID 26375667, 2015). "From the information gathered regarding their individual functions, we propose that under conditions of stress and obesity, the interactions between SUMO4 and GAPDH play a role in regulating insulin and EGFR signalling to increase vascular complications in diabetic subjects." (PMID 19997558, 2009). "However, the role of EGFR in these cell types in obesity has not been previously investigated." (PMID 35948530, 2022). "This does not exclude that there is an effect of the VSMC EGFR in an HFD, as a major impact of angiotensin II in obesity is on the perfusion of the microvasculature and these vessels were not the scope of our study." (PMID 37626737, 2023).
oesophageal cancer (56 papers, 1999 to 2025). "Analysis of more than 200 studies involving more than 20,000 patients revealed that the expression of EGFR was also associated with reduced recurrence-free survival in patients with head and neck, ovarian, cervical, bladder and oesophageal cancers." (PMID 24354805, 2013). "Several studies have investigated the status of EGFR mutations in esophageal carcinoma and appear to suggest that EGFR mutations in esophageal carcinoma are rare but do exist." (PMID 24103528, 2013). "Together with other findings, our data indicated that EGFR mutations exist in esophageal carcinoma at low levels, which is difficult to detect by conventional DNA sequencing." (PMID 24103528, 2013). "However, several studies have investigated the status of EGFR mutations in esophageal carcinoma and they mostly showed a very low frequency of EGFR-activating mutations." (PMID 24103528, 2013). "Furthermore, chemotherapy induction and the possibility to optimise the association with EGFr antibody warrants further studies with the combination irinotecan–cisplatin and radiotherapy in patients with oesophageal cancer." (PMID 16967056, 2006). "In LC cells, ADAMTS18 overexpression decreased EGFR/AKT activation, while secreted ADAMTS8 was found to reduce EGFR/MAPK/ERK signalling in oesophageal cancer cells." (PMID 38948119, 2024). "As a new type of approach, targeted therapies have been confirmed to play an essential role in treating oesophageal cancer, such as cetuximab targeting the EGFR." (PMID 36291586, 2022). "By blocking the ADAM17-mediated shedding of HB-EGF (ligand of the EGF receptor/EGFR), MEDI3622 exhibits antitumour activity in xenograft models of EGFR-dependent colorectal and oesophageal cancer." (PMID 35158891, 2022). "Even though several studies regarding first-generation EGFR TKIs, including gefitinb, erlotinib, and icotinib, have been conducted in advanced esophageal carcinoma, limited benefits were observed." (PMID 34688250, 2021). "YAP‐induced up‐regulation of the epidermal growth factor receptor (EGFR) plays an important role in conferring drug resistance to oesophageal cancer cells." (PMID 32281270, 2020). "As overexpression of EGFR has been identified in up to 30% of esophageal tumors, therapies targeting the EGFR pathway have been of high interest in esophageal carcinomas." (PMID 31683722, 2019). "This agent resulted in an additive increase in cytotoxicity in oesophageal cancer cells that overexpress EGFR." (PMID 29808844, 2018). "First, immunoblotting and densitometry were used to confirm relative EGFR expression in three different oesophageal cancer cell lines." (PMID 29808844, 2018). "Nanoparticles radiolabelled with 111In are taken up preferentially by EGFR-overexpressing oesophageal cancer cells, where they exhibit radiotoxicity through the generation of cellular DNA damage." (PMID 29808844, 2018). "The conjugation of hEGF aimed to achieve increased levels of nanoparticle uptake in oesophageal cancer cells that overexpress EGFR compared to cells with normal EGFR levels." (PMID 29808844, 2018). "Substantially decreased uptake and radiotoxicity of nanoparticles towards normal human fibroblasts and oesophageal cancer cells with normal EGFR levels is observed." (PMID 29808844, 2018). "First, we investigated the expression level of EGFR in esophageal carcinoma cells KYSE-450 and KYSE-150." (PMID 30596104, 2018). "Two randomized clinical trials “EXPAND” and “REAL3” evaluated efficacy of an anti-EGFR monoclonal antibody (panitumumab or cetuximab) in combination with chemotherapy in patients with advanced gastric and oesophageal cancer." (PMID 27514667, 2016). "There are no ethnic differences in the expression levels of VEGF, HER-2, and EGFR mRNA in the adjacent tissues to esophageal carcinoma." (PMID 26099724, 2015).